POLE (DNA polymerase epsilon, catalytic subunit)
Diseases named in the same sentence as POLE in open-access papers (continued):
Sharing a sentence is not in itself a finding about the gene and the disease.
cancer (continued). "Genetic instability such as MSI, POLE, and POLD1 defects lead to an increased mutation burden which arises as a leading biomarker of response to immune blockade inhibitors, new drugs that have improved outcomes in several cancer types through immune stimulation." (PMID 30275357, 2018). "However, similar exclusion of families carrying APC, MUTYH or POLE and POLD1 mutations because known cancers other than CRC are rare or unknown in these syndrome, and exclusion based on CRC would have defeated the purpose." (PMID 28701784, 2017). "In addition to validating our results in further independent EC series, it will be important to determine whether an enhanced cytotoxic T cell reaction also occurs in other POLE proofreading-mutant cancers." (PMID 27141333, 2016). "Thus, while much remains unknown, further study of POLE-mutant cancers may provide insights into antitumor immune response and evasion that are generalizable more broadly, with potential benefits for a wide range of cancer patients." (PMID 27141333, 2016). "Likewise, cancers carrying the POLEP286R allele exhibited an overrepresentation of G:C→T:A substitutions at AGA:TCT motifs, supporting a DNA sequence-specific proofreading defect for this particular POLE mutation." (PMID 24705290, 2014). "Current gene- and disease-informed specifications are under development for the MUTYH, POLE and POLD1 genes, and other adenomatous and hamartomatous polyposis genes will follow to optimize clinical management and opportunities for cancer prevention." (PMID 40237887, 2025). "We prepared EBV-transformed cell lines from the primary lymphocytes of 3 patients bearing candidate variants (henceforth referred to as the POLD1/POLH cell line, POLE cell line, and POLK cell line) and from several age-and gender-matched cancer-free controls." (PMID 37095444, 2023). "POLE, POLD1 have been considered as predictive biomarkers for immunotherapy in many cancer types, including melanoma, colorectal, and endometrial cancers." (PMID 35328658, 2022). "Taken together, these cases constitute four patients with a digenic inheritance of a POLE/POLD1 PV and an MMR gene PV and an exceptionally young age of cancer onset." (PMID 36291559, 2022). "Regardless, no studies have focused on the clinical pattern of POLE mutations, and limited data are available to characterize Asian patients or examine potential differences between racial groups, all of which are important for providing precision cancer medicine." (PMID 33125191, 2021). "The 2013 TCGA analysis of endometrial carcinomas (ECs) identified four main molecular subgroups: DNA polymerase ε (POLE) ultramutated, microsatellite instable (MSI-H), carcinomas with high somatic copy number alterations (CN), and carcinomas with low CN." (PMID 33572888, 2021). "As the pathogenic significance of the majority of non-EXO cancer-associated POLE mutations remains unknown, our work suggests that modeling these mutations in yeast can provide an effective way to distinguish their genomic instability effects between DNA hyper-rearrangements versus hyper-mutations." (PMID 32415104, 2020).
cancer (continued). "Two DDR-related genes (POLE and POLD1) were also shown to correlate well with WES-TMB in pan-cancer types." (PMID 32843031, 2020). "Thus, it is likely that the POLE-L424V variant is seen frequently in cancers not because it is more pathogenic than other POLE mutations, but because it is generated more frequently at the DNA level, either during normal DNA replication or during various stress responses." (PMID 29352080, 2018). "Since arriving on the market in 2011, the Ion Torrent PGM, a benchtop sequencer, has already been successfully used for the targeted resequencing of cancer genes, such as BRCA, BRAF, POLE and POLD1." (PMID 24705691, 2014). "These treatments were offered based on comprehensive genomic profiling, which identified POLE and ATM mutations associated with many malignant tumors, a finding that has not been previously reported." (PMID 38933440, 2024). "Although variants in POLM have not been directly associated with cancer risk, it is a putative predisposition gene since variants in other DNA polymerase genes (POLD1 and POLE) have already been related to CRC risk." (PMID 39408606, 2024). "They lack the high mutation burden of POLE and MSI-high cancers and do not exhibit the marked copy-number alterations or specific mutations of the other categories." (PMID 38539507, 2024). "Candidate variants in the ExoD of POLE and POLD1 predispose to cancer and exhibit a strong mutagenic effect, however, the role of non-ExoD variants in mutagenesis and cancer risk has been controversial." (PMID 37095444, 2023). "In addation, CAT, POLE, NTHL1, ATP7B, ISCA2, NDUFA1 and NDUFB2 have also been reported to play a key role in the development of cancers." (PMID 36685880, 2022). "Here, the authors show that in human cancer cells POLE is dispensable for the replicative helicase assembly but not for replication initiation, which requires the non-catalytic domain of POLE1." (PMID 36402816, 2022). "POLE and RAD50 mutations were identified as independent prognostic indicators regardless of cancer type and MMR status." (PMID 33960179, 2021). "DDR genes including ATM, ATR, CHEK2, POLE, and POLQ could serve as potential biomarkers of ICI response, but their distinct and cancer-specific effects need to be investigated further." (PMID 34095878, 2021). "We reasoned therefore that the important role of POLE in DDR, which may be closely related to the development of ccRCC, should be exploited as a powerful biomarker in cancer diagnosis and prognosis." (PMID 34950188, 2021). "Only the POLE p.Y1078fs (AC/AN = 1/17,692, AF = 0.0056%) and BRIP1 p.E1222fs (AC/AN = 11/19,232, AF = 0.057%) were present exclusively in the East Asian ancestry of gnomAD-non-cancer dataset." (PMID 32471518, 2020). "Furthermore, POLE and POLD1 defects have been reported to be instrumental in the development of cancer, characterized by increased levels of transversions (G:C→T:A and A:T→C:G) and transitions (G:C→A:T)." (PMID 33339161, 2020). "Even though not significant, POLE mutated and MMR‐D carcinomas had a favorable outcome, in line with earlier studies." (PMID 32022266, 2020).
cancer (continued). "Although this is commonly seen in non-smoking associated cancers, we wish to stress the close link between transitions (mainly C-to-T) and MSI as well as POLE/POLD1 mutations in men." (PMID 31581674, 2019). "First, we noted that POLE/POLD1 exonuclease domain mutations were frequently clonal (13/15 POLE and 8/10 POLD1 mutations had an estimated cancer cell fraction [CCF] > 0.9) and that non-clonal POLE/POLD1 mutations appeared to be non-functional passenger events." (PMID 29717118, 2018). "Since the precise functional role of POLE aberrations in cancer development and specifically in CRC has not yet been fully understood, a satisfactory biological explanation of our results is challenging." (PMID 25124163, 2014). "Of the 186 patients without germline P/LP variants and available cancer genomes–exomes, 41/186 patients had a somatic variant in the DNA damage response pathway (ATRX, ATM, PPM1D, POLE) and 21/186 had a variant in the MAPK-ERK pathway (BRAF, NF1, PTPN11, MAPK12)." (PMID 40072012, 2025). "However, the negative correlations observed in these cancers were no longer significant after excluding MSI-high and POLE-mutated tumors." (PMID 40420266, 2025). "Additionally, we assessed the allele frequencies of the genes in the gnomAD non-cancer cohort (n = 134 187), which showed significant differences in BRCA1, BRCA2, CHEK2, MUTYH, MSH6, POLE, and ERCC3 genes in comparison to our non-HBOC groups." (PMID 39148954, 2024). "Similarly, the genes for proofreading polymerases POLE and POLD1 are mutated in 7.5% and 4.5% of PIK3CA mutated cancers versus 2.2% and 0.6% of PIK3CA non-mutated cancers." (PMID 33435133, 2021). "However, multivariate Cox regression with TMB, cancer type, and MMR status showed that MMR status, and POLE and RAD50 mutations were no longer independent prognostic indicators, whereas TMB was an independent prognostic indicator." (PMID 33960179, 2021). "Thus, we performed multivariate Cox analyses without TMB (with each DDR gene), and identified POLE and RAD50 mutations as independent prognostic indicators regardless of cancer type and MMR status." (PMID 33960179, 2021). "However, multivariate Cox regression with TMB, cancer types, and MMR status showed that POLE and RAD50 mutations were not independent prognostic indicators, whereas TMB was an independent prognostic indicator." (PMID 33960179, 2021). "No cancer-related deaths occurred in the POLE mutant subgroup." (PMID 33232359, 2020). "We next aimed to determine whether POLE/POLD1- and MSI-mediated mutagenesis occurred simultaneously in the same cancer cells, or whether the events were separated spatially (i.e., occurring in distinct subclones) or temporally (i.e., defective in non-overlapping time intervals)." (PMID 29717118, 2018). "Previous studies investigating the mechanism of the transcriptional regulation of POLE expression and mutations in carcinogenesis show that POLE or POLD1 mutations serve as negative prognostic markers and may predict a survival benefit from ICI therapy across diverse cancers." (PMID 34950188, 2021). "The relationship between TMB and HRD varied by cancer type, due to the negative correlation of MSI-H and POLE alterations with HRD scores, consistent with TCGA and Westphalen’s analyses." (PMID 40420266, 2025).
gastrointestinal tumors (4 papers, 2020 to 2024). "Research on gastrointestinal tumors has revealed that individuals with polymerase ε (POLE) mutations are prone to developing colorectal cancer (CRC) and other gastrointestinal tumors." (PMID 39768855, 2024). "Lesser CD8+ and gamma-interferon gene expression signatures have also been observed in gastrointestinal tumors with a large single nucleotide variant (SNV) burden that was attributed largely to POLE exonuclease mutations." (PMID 32838755, 2020).
gynecologic tumors (2 papers, 2024). "Ongoing studies are examining POLE hotspot mutations among many non-gynecologic tumors, although the impact of such mutations on clinical outcomes is still a topic of debate." (PMID 39239272, 2024).
heart disease (1 paper, 2020). "For example, while CDK13, CHD4, KDM5A, and SCN10A are related to familial heart disease, CFH, DGUOK, and POLE are related to familial vascular disease." (PMID 31941532, 2020).
infection (1 paper, 2020). The state of being infected such as from the introduction of a foreign agent such as serum, vaccine, antigenic substance or organism. "Our data suggest that the accessory components (RFC2, RFC3, RFC5, PCNA), polymerases (POLD1, POLD2, POLD3, POLE, POLE2, POLE4), and ligase LIG1, were downregulated during infection, for which the downregulation of RFC5, POLD1, POLD2, POLD3, POLE, and LIG1 was CagA-related." (PMID 33339161, 2020).
POLE also shares sentences with these, for which no sentence is quoted: adenocarcinoma (6 papers); astrocytoma (5); familial melanoma (4); metastatic colorectal cancer (4); non-small cell lung carcinoma (4); oligodendroglioma (4); Adrenal insufficiency (2); Cowden disease (2); giant cell glioblastoma (2); hematologic malignancy (2); hereditary non-polyposis colorectal cancer (2); juvenile polyposis syndrome (2); Metaphyseal dysplasia (2); primordial dwarfism (2); rectum adenocarcinoma (2); small cell lung carcinoma (2); tumor syndrome (2); type 2 diabetes (2); adrenal hypoplasia (1); adrenal hypoplasia congenita (1); anaplastic astrocytoma (1); anaplastic oligoastrocytoma (1); anemia (1); aneuploidy (1); angiomyolipoma (1); autosomal recessive disease (1); brain glioma (1); café-au-lait macules (1); cancers of the brain (1); carcinoma of the gallbladder (1).
A further 50 diseases each share a sentence with POLE in 1 paper.